MIR4743 (microRNA 4743)
Synonyms: hsa-mir-4743
Gene: MicroRNA gene on chromosome 18 (48,670,600 to 48,670,668, forward strand). Ensembl gene ENSG00000266276.
Homologues: Orthologues: chimpanzee MIR4743 (100% identical), macaque MIR4743 (100% identical).